BCL2 (BCL2 apoptosis regulator)
Diseases named in the same sentence as BCL2 in open-access papers (continued):
Sharing a sentence is not in itself a finding about the gene and the disease.
tumor (continued). "Moreover, Salen-Mn treatment (50 mg/kg) obviously increased expression of cleaved PARP, Bax and decreased expression of Bcl-2 in the xenograft tumor tissues comparing with control group treated with vehicle, suggesting that Salen-Mn also elevated cell apoptosis in vivo." (PMID 29156794, 2017). "However, the mechanisms by which Bcl-2 regulates tumor EMT is not well understood." (PMID 28032603, 2017). "Additionally, the formation of the Bcl-2/Twist1 complex is stimulated when tumor cells are hypoxic." (PMID 28032603, 2017). "Further BCL2 (dis-)regulation might be due other effects, such as de novo tumor mutations, which were not analyzed in the present study." (PMID 28396899, 2017). "Furthermore, EPO also leads to increased expression of anti-apoptotic proteins such as bcl-2 and bcl-XL and their activation is likely to account, at least in part, for the enhanced anti-tumour effect of anthracycline-based chemotherapy which accompanies a pCR." (PMID 29108271, 2017). "In addition, Bcl-2 overexpression is correlated with a low apoptosis rate of tumor cells." (PMID 28464919, 2017). "A peptide designed to specifically block the interaction between the MHV68-encoded homolog of Bcl-2 M11 and BECN1 (therefore, preventing M11-mediated downregulation of autophagy) could be used to both restore the tumor suppressor activity of BECN1 and to limit the reservoir of viral latency." (PMID 29207540, 2017). "Co-treatment with Nutlin-3 and Bcl-2 inhibitor ABT-737 has been shown to greatly enhance the sensitivity to apoptosis of cancer cells with high MDM2 levels, suggesting that the combined inhibition of MDM2 and Bcl-2 could be a multi-target-based anticancer strategy to trigger tumor death." (PMID 27019364, 2016). "If the tumor adaption model were dominant, we would expect a lower recurrence rate in the Bik-high patient subgroup with low Bcl-2 and presumably unencumbered apoptotic signalling, whereas the Bik-high patients with high Bcl-2 would show significantly higher recurrence rates." (PMID 27120789, 2016). "Interestingly, mutation rates in apoptotic proteins such as death receptors or BCL-2 proteins are low indicating that many cancer cells have intact apoptotic machinery which if unblocked could efficiently kill tumour cells." (PMID 27140313, 2016). "Here, the authors show that, in intestinal stem cells, Bcl-2 alleviates apoptotic priming induced by the loss of the tumour suppressor Apc in ISCs and that the absence of Bcl-2 or pharmacological blockade of Bcl-2 can inhibit the intestinal tumorigenesis driven by the Apc-loss." (PMID 26956214, 2016). "In addition, previous studies showed that IKK-NFκB signaling pathways may lead to downstream upregulation in expression of certain tumor-promoting cytokines and survival genes, including BCL2 and inflammatory chemokines (as predicted in this study)." (PMID 27078000, 2016). "The results have shown that GLN supplementation caused a significant decrease by 57% in tumor GSH levels and similar ratio GSH/oxidized GSH (GSSG) accompanied by upregulation of Bax and caspase-3 (apoptosis induced factors) and downregulation of Bcl-2 (apoptosis inhibiting factor)." (PMID 26583064, 2015). "Therefore, the blocking of Bcl2 can restore the apoptotic process in tumor cells." (PMID 26074734, 2015). "We next asked whether RTA 405 treatment increases the levels of IKKβ and BCL2 in tumor cells." (PMID 26301506, 2015). "An increase in Bcl-2 expression may promote tumor invasion via increased MMP2 expression." (PMID 25826088, 2015).
tumor (continued). "Unfortunately, tumor cells can become resistant to these therapies, allowing them to efflux chemotherapeutic agents, modify drug targets by altering expression of genes and proteins involved in carcinogenesis, and increase production of anti-apoptotic proteins such as Bcl-2 and Bcl-Xl." (PMID 25918934, 2015). "However, Bax/Bcl-2 ratio was statistically correlated with age and tumor location." (PMID 25864810, 2015). "In the present study, we used cell and animal models to test the possibility that stabilization of Bcl-2 protein by phosphorylation at Serine 87 by PXN-mediated ERK activation may be responsible for tumor progression and metastasis via upregulation of MMP2 expression." (PMID 25826088, 2015). "Therefore, we hypothesized that bcl-2 expression may reflect tumor characteristics, and thus, serve as a reliable indicator for predicting recurrence." (PMID 24555747, 2014). "Questions raised over the roles of BCL-2 in autophagy are: whether overexpression of BCL-2 in human tumors inhibits both apoptosis and autophagy; and whether inhibition of apoptosis by overexpression of BCL-2 could activate the autophagic pathway in favor of prolonged tumor cell survival." (PMID 25362242, 2014). "Therefore, we hypothesized that bcl-2 might reflect the biological nature of the tumor, and would serve as a reliable indicator for predicting recurrence." (PMID 24555747, 2014). "We then assessed whether the expression of Bcl-2, Bcl-xL, survivin, p21 and cyclin D1 correlates with various clinical and pathologic parameters, including gender, location and size of the tumor, lymph node metastasis, histologic grade, depth of tumor invasion/clinical stage and overall survival." (PMID 25438156, 2014). "The apoptotic pathways by which MDA-7/IL-24 kills tumor cells remain to be fully understood; however, current evidence suggests an inherently high degree of complexity and an involvement of proteins important for the onset of growth inhibition and apoptosis, including Bcl-XL, Bcl-2 and Bax." (PMID 24527085, 2014). "In the animal studies, the folate-targeted co-delivery of Bcl-2 siRNA and DOX caused a significant down-regulation of the Bcl-2 gene and also up-regulated the pro-apoptotic Bax gene, which increased the activated caspase-3 levels significantly, resulting in cell apoptosis in the tumor tissues." (PMID 24795633, 2014). "Consequently, there is an increased expression of bcl-2, which is involved in tumor suppression." (PMID 25512116, 2014). "However TQ in combination with bortezomib was found to suppress the expression of Bcl-2 in MM tissues, which may also account for its tumor inhibitory effects." (PMID 24504138, 2014). "However, in some types of tumour, BCL-2 seems to play both oncogenic and suppressive role." (PMID 25005788, 2014). "Furthermore, tumor cells often switch expression from BCL-2 to BCL-xL." (PMID 24637737, 2014). "Furthermore IL-6 may also provide tumor cells with mechanisms to escape cell death induced by stress and cytotoxic drugs, such as increased expression of several survival proteins, i.e. Bcl-2, Bcl-xL, Mcl-1, survivin, and XIAP." (PMID 23517603, 2013).
tumor (continued). "The nuclear factor-kappa B (NF-κB) transcription factor plays an important role in tumor escape and resistance to chemotherapy and this factor regulates several pathways that promote tumor survival including some antiapoptotic proteins such as Bcl-2 and Bcl-XL." (PMID 23445492, 2013). "Perhaps, the expression of a genetic tumor marker, such as bcl-2, may hold the key to a cure." (PMID 23533909, 2013). "Moreover, the cutoff in the number of positive cells defining a tumour with Bcl-2 overexpression often varies according to the investigators, which may lead to biased conclusions." (PMID 24370277, 2013). "It has been reported that aberrant STAT3 activation promotes uncontrolled tumor cell growth and survival through multiple mechanisms, including increased expression of oncogenes, such as c-myc, Skp2, and cyclin D1, as well as antiapoptotic proteins, including Bcl-2, Bcl-xL, Mcl-1, and survivin." (PMID 24386318, 2013). "The materialisation of the idea of interfering with expressions/activities of specific Bcl-2 targets in cancerous cells challenges us to develop a complete understanding of the behaviour of Bcl-2 proteins in response to different anticancer agents in various neoplasms." (PMID 23441183, 2013). "However, when targeting two antiapoptotic Bcl-2 proteins simultaneously, the approach to identify tumor-specific combinations turned out to be very important: Inhibition of Mcl-1 in combination with the inhibitor ABT-737 strongly induced cell death, which was also observed by others." (PMID 22292048, 2012). "In addition, increases in TXB2 expression have been associated with increased lipid peroxidation and bcl2 expression, suggesting that circulating TXB2 levels may promote tumour formation, partly via apoptosis evasion." (PMID 21388528, 2011). "For example, Clément MV and his groups demonstrated that overexpression of Bcl-2 increases intracellular O2- and inhibits apoptotic acidification and cell death, while decrease in intracellular superoxide sensitizes Bcl-2-overexpressing tumor cells to apoptotic killing." (PMID 21504623, 2011). "An explanation may be that poorly differentiated tumors depend on other prosurvival pathways, and decreased Bcl-2 expression merely is a marker of aggressive tumor behaviour rather than mechanistically associated with aggressive biology." (PMID 21304176, 2010). "Bcl-2 protects against diverse cytotoxic insults, including γ and UV-irradiation, cytokine withdrawal, dexamethasone, staurosporine and cytotoxic drugs, while pro-apoptotic family members like Bax may act as tumour suppressors." (PMID 20441573, 2010). "Mechanistic studies indicated that treatment of PC-3 cells/tumours with VN/66-1+MS-275 caused DNA damage (upregulation of γH2AX), hyperacetylation of histones H3 and H4, upregulation of retinoic acid receptor-β, p21WAF1/CIP1, E-cadherin, and Bad and downregulation of Bcl-2." (PMID 18349838, 2008). "Thus, a high BSI combined with either negative or positive Bcl-2 levels was associated with both improved DFS and OS as compared to tumours that showed a low BSI combined with either Bcl-2-negative or -positive samples." (PMID 17426704, 2007). "Moreover, Bcl-2 inhibitors may be especially useful in tumours where the perforin/granzyme-B system is the main functional pathway available for target cell killing." (PMID 17311012, 2007).
tumor (continued). "As Bcl-2 overexpression may protect malignant cells from antitumour immune responses, we investigated whether coexposure to both Bcl-2 inhibitor and activated immune cells could increase tumour-cell killing." (PMID 17311012, 2007). "Although there have been many studies on the prognostic value of each of Bcl-2 and p27 protein expressions in various human cancers, only a few studies have been conducted regarding the relationship between Bcl-2 and p27 protein expressions in the tumor specimens." (PMID 16839413, 2006). "Resistance to TRAIL-induced apoptosis in various tumours was described to be caused by the deregulation of diverse signalling molecules such as down-regulation of TRAIL-receptors, caspase-8, caspase-10 or Bax, or over-expression of c-FLIP, Bcl-2, Bcl-xL or survivin." (PMID 16930472, 2006). "Interestingly, pre-incubation of cells with the CC or poly I:C did not significantly change the reduction of Bcl-2 expression caused by tumor supernatants." (PMID 16417648, 2006). "Therefore, Bcl-2 expression levels might play a critical role in the modulation of TRAIL sensitivity of tumour cells." (PMID 15651986, 2005). "As in case of Akt-1, we could not find any significant association of pAkt with nodal status, tumour size, ER, PgR or Bcl-2 but we did find a strong negative association with SPF." (PMID 11870534, 2002). "Bcl-2 protein expression in epithelial malignancies is probably a reactive and reversible cellular mechanism to suppress pro-apoptotic oncogenic changes, which may be stronger in some tumours." (PMID 12454767, 2002). "Therefore, it will be important to determine whether other human neoplasms with Bcl-2 overexpression are also sensitive to the apoptotic action of taxotere." (PMID 11875716, 2002). "Since in each tumour, epithelial and spindle cell components harbour the same type of translocation t(X;18) the present findings suggest a shifting of the anti-apoptotic role from BCL2 to c-KIT gene during the transition from the uncommitted spindle to the differentiated epithelial cells." (PMID 11487273, 2001). "However, androgen ablation rarely cures patients, most of whom will experience recurrence due to takeover of the tumor mass by androgen-independent tumor cells as well as the emergence of apoptosis-resistant clones as a result of further genetic alterations such as bcl-2 amplification." (PMID 11500787, 2001). "We hypothesized that unexplained increases in nucleoside triphosphates (NTP) observed by 31P magnetic resonance spectroscopy (MRS) after treatment of tumours by DNA-damaging agents were related to chemotherapy-induced up-regulation of the bcl-2 gene and DNA damage prevention and repair processes." (PMID 9652754, 1998). "Tumour cells often escape cell death by overexpressing anti-apoptotic members of the BCL-2 protein family, particularly BCL-2, BCL-xL, and MCL1." (PMID 41937490, 2026). "Immunohistochemical analysis showed that tumor tissues treated with high doses of VER exhibited reduced levels of PCNA, Bcl-2, vimentin, MMP-2, p-AKT, and p-PI3K compared with the control group." (PMID 41158757, 2026). "Accordingly, in vivo treatment of mice bearing solid tumours with a combination of the Bcl-2/Bcl-xl inhibitor AZD0466 and anti-PD-L1 immunotherapy resulted in enhanced anti-tumour effects and improved survival compared to equivalent monotherapies." (PMID 41495028, 2026). "The free radical scavenging potential of Salvia coccinea and apigenin is responsible for reduced oxidative stress and tumor cell metastasis modulated through PARP-cleavage, caspase-3, ERK, CDK-1, JAK2/STAT3, Bax/Bcl-2, AMPK, and Wnt/β-catenin pathways." (PMID 41640995, 2026).
tumor (continued). "In vivo, EVs accelerated tumor growth and activated prosurvival (p-AKT, BCL-2), angiogenic (VEGFA, CD31), and epithelial-mesenchymal transition-associated (vimentin) pathways." (PMID 41828681, 2026). "Tumors IA-treated showed a reduction in size, weight, and number of tumor cells; the expression of HKII and Bcl-2 decreased, while that of Caspase-3 increased." (PMID 40801624, 2025). "The expression of the antiapoptotic protein BCL2 and proinvasion-related proteins Snail and N-CAD was upregulated in 22RV1 and PC-3 tumor cells, while those of the proapoptotic protein BAX and invasion-related protein E-CAD were downregulated." (PMID 40548257, 2025). "In vitro and in xenograft tumours, HSP inhibited the proliferation of gastric cancer cells by inducing apoptosis through a dose-dependent increase in the Bax/Bcl-2 ratio, cyt-c, caspase-3, caspase-9, AIF, and Apaf-1 via a mitochondrial-dependent mechanism." (PMID 40427522, 2025). "Both BCL2 and BCL-XL are overexpressed in several cancers and contribute to tumor cell survival and therapy resistance by preventing apoptosis in response to DNA damage, oxidative stress, or cytotoxic treatments." (PMID 40940829, 2025). "Apoptosis plays a central role in the anti‐tumour response, with key regulators such as BAX, BCL‐2, and Cleaved caspase‐3 often being evaluated in mitochondrial apoptosis way." (PMID 40804775, 2025). "PCNA, BCL2, TRAF2, XIAP and FKBP5 expression levels in whole RNAs extracted by 36 tumor tissue samples were quantified as relative expression, using expression from healthy donor PBMCs as a reference sample (=1)." (PMID 41256864, 2025). "MT also modulates apoptosis-related proteins (e.g., Bax, Bcl-2), inhibits telomerase activity, and promotes ANXA3 expression, all of which contribute to tumor suppression." (PMID 40564074, 2025). "This pro-apoptotic phenotype correlated with upregulation of pro-apoptotic BAX, and downregulation of anti-apoptotic BCL-2, indicating RSF1 sustains tumor cell survival by regulating the mitochondrial apoptotic pathway." (PMID 40862741, 2025). "When we verified BECN1 and BCL2 expression levels in the M0, M1 and M2 macrophage subtypes in DLBCL and non-tumor control samples, we found that they were overexpressed in M0 and M1 but not in M2 macrophages." (PMID 41415285, 2025). "In the present case, the tumor cells demonstrated immunoreactivity for CK5/6, p63, and Bcl-2, findings that are consistent with previously reported immunophenotypic characteristics of this neoplasm." (PMID 41568371, 2025). "In conclusion, our findings indicate that BCL2 targeting with ABT-199, in combination with ALKi, can significantly reduce tumor cell survival in Ba/F3 EML4-ALK cell models." (PMID 39836700, 2025). "Tumor cells universally expressed CD20, with frequent positivity for CD19 (95.7%), CD79a (100%), MUM1 (83.8%), and BCL2 (92.1%), while CD10 (17.5%) and CD30 (10%) were less common." (PMID 41487580, 2025). "HOXA11-AS also upregulated the mRNA levels of tumor suppressor and apoptotic regulatory genes PTEN, BCL2 and Caspase3." (PMID 40457415, 2025). "The combined management of RES with temozolomide caused cell cycle arrest, decreases of MMP9, and anti‐apoptosis protein Bcl‐2 in the human GB cell line (SHG44), and reduced the volume of the tumor in an orthotopic xenograft model of GB." (PMID 40400263, 2025). "In this case, the tumor cells expressed CD79a and PAX-5, along with high expression of c-Myc and Bcl-2, which closely resembled the characteristics of “double-expressor DLBCL” in terms of pathological morphology." (PMID 41561755, 2025). "Upregulation of Bcl-2 and Bcl-xL via IL-4/STAT6 signaling is therefore a key mechanism by which tumor cells evade apoptosis and sustain their growth under therapeutic pressure." (PMID 40864740, 2025).